CDY2A (chromodomain Y-linked 2A)
Description:
May have histone acetyltransferase activity.
Synonyms: CDY2; CDY
Gene: Protein-coding gene on chromosome Y (18,025,787 to 18,027,746, forward strand). Ensembl gene ENSG00000182415.
Subcellular location: Nucleus
Gene Ontology:
Molecular function: histone H3K27me3 reader activity; histone H3K9me2/3 reader activity; transcription corepressor activity; protein-lysine-acetyltransferase activity
Biological process: negative regulation of peptidyl-lysine crotonylation; spermatogenesis; chromatin organization; negative regulation of DNA-templated transcription
Cellular component: nucleus
Homologues: Orthologues: macaque CDY (83% identical), mouse Cdyl (61% identical), zebrafish cdyl (47% identical), rat AABR07039112.1 (40% identical), Caenorhabditis elegans B0272.4 (13% identical), Drosophila melanogaster Dci (12% identical), Drosophila melanogaster CG8778 (10% identical), Drosophila melanogaster Srlp (10% identical), Caenorhabditis elegans ech-5 (10% identical), Drosophila melanogaster CG14787 (9% identical), Caenorhabditis elegans ech-3 (9% identical), Drosophila melanogaster HIPP1 (9% identical), and 1 more. Paralogues in human: CDY2B (100% identical), CDY1B (98% identical), CDY1 (96% identical), CDYL (62% identical), CDYL2 (38% identical), ECHS1 (14% identical), ECHDC2 (12% identical), ECHDC3 (12% identical), HIBCH (12% identical), ECH1 (12% identical), AUH (11% identical), ECHDC1 (10% identical), and 1 more.
Diseases named in the same sentence as CDY2A in open-access papers:
CDY2A is named in the same sentence as 2 diseases in open-access papers, as found by Europe PMC text mining. Sharing a sentence is not in itself a finding about the gene and the disease.
CDY2A shares sentences with these, for which no sentence is quoted: Azoospermia (1 paper); Infertility (1).